WNT1 (Wnt family member 1)
Diseases named in the same sentence as WNT1 in open-access papers (continued):
Sharing a sentence is not in itself a finding about the gene and the disease.
tumor (continued). "The transient suppression of Wnt-1 tumor growth by Rapamycin suggests that it is unlikely that these mechanisms play a significant role in this model." (PMID 18570671, 2008). "The effect of Rapamycin on the mTOR pathway was further examined in short-term primary cultures of Wnt-1 tumor cells and in two clonal cell lines established from these tumors." (PMID 18570671, 2008). "The effect of Rapamycin on growth of Wnt-1 tumors was examined in syngeneic C57BL/6 mice implanted with Wnt-1 tumor cells subcutaneously (s.c.)or into mouse fat pad #4 (MFP)." (PMID 18570671, 2008). "Tumor cell behavior and collagen morphology in this model were similar to observations from the Wnt-1 mouse tumors." (PMID 17190588, 2006). "Expression of Wnt1 is reduced in tumor tissues, which may contribute to the advancement of disease by weakening the inhibition of cancer cell migration and invasion." (PMID 40943055, 2025). "However, the lncRNA GATA3-AS1 sponges miR-30b-5p, which in turn leads to the upregulation of the target gene Tex10, regulating tumor cell growth, viability, proliferation, invasion, apoptosis, and stemness, as well as Wnt1/β-catenin signaling." (PMID 41440381, 2025). "Tumorigenic growth in the MMTV-Wnt1 model is driven by high levels of Wnt1 expression, and treatment with inhibitors of Porcupine (Porcn), a protein essential for Wnt acylation and subsequent secretion, blocks tumor growth." (PMID 41218118, 2025). "Similarly, Wnt1 is overexpressed in human HCC tissues and hepatoma cell lines, with its increased levels correlating with a higher risk of tumor recurrence following curative resection." (PMID 40943055, 2025). "Additionally, Tlr2-/-MMTV–Wnt1 (Tlr2-/-Wnt1) mice exhibit markedly reduced tumor formation compared with that of their Tlr2+/+MMTV–Wnt1 (Tlr2+/+Wnt1) littermates, with median tumor-free days of 269 and 137, respectively." (PMID 38347830, 2024). "Anti-Wnt1 is a monoclonal antibody specific for Wnt1 that inhibits H460 NSCLC tumor growth in mice." (PMID 38612911, 2024). "Notably, in the Wnt1 tumor syngeneic mouse model, E-7386 alone exhibited significant antitumor activity, whereas the combination of E-7386 and anti-PD-1 mAb enhanced antitumor effects beyond those achieved by either treatment alone." (PMID 39407454, 2024). "To conclude, we found that the assessment of WNT-1 in the cell membrane may be useful for exclusion of grade 3 neoplasms, whereas cytoplasmic WNT-1 and nuclear mTOR may be used as indicators for confirmation of grade 3 neoplasms." (PMID 37176048, 2023). "The cytoplasmic expression levels of WNT-1 also tended to increase with tumor grade." (PMID 37176048, 2023). "Many in vitro and in vivo studies show that in different tumor types, such as colorectal, lung, breast, or hepatocellular cancer, specific WNTs, including WNT1, WNT2, WNT3A, WNT6, WNT8B, WNT7B, and WNT16B, can activate canonical Wnt signaling and support tumor proliferation." (PMID 36982422, 2023). "According to multiple logistic regression analysis, membranous WNT-1 was found to be negatively associated with a high-grade tumor, and cytoplasmic WNT-1 and nuclear mTOR were found to be positively associated with a high-grade tumor (p < 0.0001)." (PMID 37176048, 2023). "Thus, either reduced Igf1r expression or reduced IGF1R function in mammary epithelium promotes metastasis of the primary Wnt1 tumor cells." (PMID 36568144, 2022).
tumor (continued). "To determine the effects of luminal epithelial specific Igf1r gene deletion in Wnt1-driven mammary tumorigenesis, we assessed tumor latency rates in the K8iKOR-Wnt1 mouse line compared to the control Wnt1 line and to our prior tumor latency data on the DN-Wnt1 mouse line." (PMID 36568144, 2022). "Notably, miR-148a is a member of the miR-148/152 family, and acts as a tumor suppressor in a variety of human solid tumors and participates in biological functions by targeting mature mRNAs, including WNT-1, Bcl-2, and KLF6." (PMID 35892859, 2022). "Furthermore, reducing P-cadherin in DN-Wnt1 primary tumor epithelial cells significantly increased tumor adhesion restoring adhesion back to the level of the Wnt1 tumor cells." (PMID 36568144, 2022). "Moreover, the levels of Wnt1 and β-catenin in the tumor tissues of the siRNA-Gm31932-174 treated group were significantly lower compared to those of the control group and the siRNA-NC group." (PMID 35393397, 2022). "Furthermore, E-cadherin expression was reduced in both luminal and basal lineages in sorted DN-Wnt1 tumor epithelial cells compared to Wnt1 cells." (PMID 36568144, 2022). "However, the effect of WNTs on tumor purity in LUSC was slightly poorer than that in LUAD, and WNT3/5A/8B/11 were positively correlated with tumor purity, while WNT1/2/4/6/7A/98/10A were negatively correlated with tumor purity." (PMID 35957916, 2022). "Thus, the data suggest that downregulation of tumor-derived exosomal miR-34c can transform fibroblasts into CAFs via targeted modulation of WNT1 to activate the Wnt signaling pathway in CCA." (PMID 34261453, 2021). "To test this hypothesis, we generated a dormancy signature from genes that were differentially up- or downregulated in dormant mouse residual tumor cells compared to primary and recurrent tumor cells, in both the HER2/neu and Wnt1 tumor models." (PMID 34088357, 2021). "For example, in NSCLC tissues and cells, miR-148a expression level is remarkably reduced, and low miR-148a expression is significantly related to the poor prognosis of the patients; functionally, miR-148a represses tumor cell migration and invasion via targeting Wnt1." (PMID 34193018, 2021). "We next asked whether the lack of enrichment for TICs in HER2/neu residual tumor cells was also true for Wnt1 residual tumor cells." (PMID 34088357, 2021). "Wnt1 had the most DCs of the tumor models, with DCs primarily falling into MC16 and MC11." (PMID 33653826, 2021). "Interestingly, dormant residual tumor cells in both the Wnt1 and HER2/neu mouse models were enriched for expression signatures associated with normal, as well as neoplastic, human mammary stem-like cells." (PMID 34088357, 2021). "Similarly, Li and Xu showed that propranolol blocked the effect of fear stress on tumor growth in PC xenograft animal models by decreasing Frizzled-1 (Fz1), Wnt-1 and vimentin protein expression." (PMID 34439102, 2021). "Additionally, we found that Thsb1 (Thrombospondin-1) expression in residual tumor cells in both the HER2/neu and Wnt1 models was elevated ~ 3-fold compared to primary or recurrent tumor cells (p values < 0.01)." (PMID 34088357, 2021). "MlphDG-liposomes were more effective than free melphalan in inhibiting tumor growth in a Lewis lung carcinoma model and in a transplanted WNT-1 tumor from genetically engineered breast cancer model in mice; in rats, the liposomes were less toxic and better tolerated." (PMID 33915726, 2021). "We analysed the expression of OCT4, SOX2, CK14, CK18, and WNT1 in the tumour tissues." (PMID 32307830, 2020). "Knocking down Wnt-1 and Wnt-3A suppresses tumor proliferation." (PMID 33262947, 2020). "As a member of the Wnt ligand gene family, Wnt1 aberrantly activates the Wnt/β‐catenin pathway in many human tumours, regulates the transcription of downstream genes and then affects cell proliferation, EMT, metastasis and the maintenance of stemness properties." (PMID 33026174, 2020).
tumor (continued). "In order to achieve the goal, the dendritic cells which infiltrated into lung adenocarcinoma were chosen as an investigating example because they were dysfunctional after interaction with Wnt1 (WNT stands for wingless-related integration site) derived from tumor cells." (PMID 32434423, 2020). "Collectively, these data indicate that miR-34a may regulate the E-P cadherin switch to inhibit in vivo tumor growth in a mouse xenograft model, at least in part, by targeting the WNT1/β-catenin pathway." (PMID 32301035, 2020). "Thus, we have unraveled a potential combinatorial therapeutic strategy of FAK ablation along with induction of ER stress in Wnt1-driven tumor cells." (PMID 32493400, 2020). "As hypothesized, Wnt1-EarlyEx tumors had a median tumor regression of 90% when treated with erlotinib at the end of the 2 week treatment period." (PMID 31213486, 2019). "Normal human LumProg cells are defined as having CD49fpos/Epcampos FACS profiles, indicating that the majority of Wnt1-LateEx tumor cells might share similar features with normal LumProg cells." (PMID 31213486, 2019). "Moreover, WNT1 and β-catenin staining of grade II and III GB samples from S24 xenograft brain sections and quantification of the pixel intensity indicated that the accumulation of WNT1 and activation of β-catenin correlates with the grade of the tumor." (PMID 31846454, 2019). "This is relevant, because CXCL12 and its receptor CXC chemokine receptor 4 (CXCR4) are present in complex lesions in PAH and CXCL12 promotes aberrant angiogenesis, endothelial proliferation and PH while others have found Wnt1 to be protective from aberrant tumor angiogenesis." (PMID 30883593, 2019). "For Wnt1-EarlyEx tumors, these two fractions accounted for only about 65% of the tumor, with the remaining 35% consisting of regions/cells that did not stain positive for either Krt5 or Krt8/18; the identify of these non-staining cell type(s) is unknown." (PMID 31213486, 2019). "We, therefore, explored whether inducing Wnt3a overexpression in LLC cells might have a similar impact to anti-tumor responses, as Wnt1." (PMID 30926812, 2019). "An interesting question that arises from our findings is whether defective T cell priming by Wnt1-exposed cDCs occurs in lymph nodes or in the tumor microenvironment." (PMID 30926812, 2019). "Broadly, we hypothesize that the mechanisms governing Wnt1-EarlyEx tumor development are probably related to early life history and/or puberty, which occurs around this time." (PMID 31213486, 2019). "Conversely, all combinations of the one Wnt1-LateEx tumor investigated gave rise to tumors." (PMID 31213486, 2019). "Therefore, we assessed the distribution of Wnt1-CD8a, Wnt1-CD8b correlations in the TCGA database, including paired tumor and tumor-free samples, by calculating the z-scores of the Spearman correlation values." (PMID 30926812, 2019). "The metabolic pathways of the Wnt1 tumors especially differed from the other tumor models." (PMID 29619217, 2018). "The scaffold-free edge retains the original tumour architecture showing the characteristic reverse bilayer phenotype of Wnt1 tumours where basal cells, defined by their expression of cytokeratin-14 (CK14), α-smooth muscle actin (αSMA) and nuclear p63, line the lumen (i-iii, lumen marked as*)." (PMID 30139956, 2018). "Wnt1-induced tumors were the most heterogeneous and clustered away from the other tumor models." (PMID 29619217, 2018). "Furthermore, it allowed 3D visualisation of tumour cells and anisotropic collagen ECM in TUBO and Wnt1 tumour fragments." (PMID 30139956, 2018).
tumor (continued). "In this study, DLD-1R and HCT-116R cells appeared to be sensitive towards regorafenib treatment as demonstrated by the decreased number of colonies, tumor spheres and stem-like phenotypes (tumor spheres and side-populations) and markers (WNT1, mTOR/STAT3, Notch1)." (PMID 30005681, 2018). "Wnt1 was mostly overexpressed in the cytoplasm of tumor cells." (PMID 28218651, 2017). "Thus, it is likely that suppression of tumor metastasis can be achieved through stabilizing the G-quadruplex forming sequence located at the WNT1 promoter." (PMID 27626678, 2016). "Wnt1 knockdown disrupted the tumor sphere formation of 4T1 cells." (PMID 26202299, 2015). "Moreover, remodeling of the actin cytoskeleton is required for tumor cell migration because the cytoskeleton pushes or pulls on substrates near cell membranes, and such changes are induced by Wnt1 knockdown." (PMID 26202299, 2015). "Additionally, the average tumor multiplicity was significantly greater in the Wnt1/iR1 bigenic mice compared to Wnt1 alone, and Wnt1/iR1 tumors grew significantly faster than the Wnt1 tumors." (PMID 26581390, 2015). "Thus, we transplanted the tumor tissues from Wnt1/iR1 spontaneous tumors to the cleared fat pads of syngeneic FvB mice." (PMID 26581390, 2015). "Upon treatment with BGJ398, Wnt1/iR1 tumor cells stopped proliferating." (PMID 26581390, 2015). "Importantly, there was a consistent and significant reduction in tumor outgrowth in the mice injected with Wnt1 knockdown cells compared with those injected with control cells." (PMID 26202299, 2015). "Therefore, miR-152, which is down-regulated by HCV core, can act as a tumor suppressor by inhibiting cell proliferation possibly through regulating Wnt1 in HCC." (PMID 24416131, 2014). "Interestingly, the Wnt10b tumorigenic mouse model contrasts the MMTV-Wnt1 model, in part, because Wnt1-driven tumours have been reported to express hormone receptors." (PMID 23307470, 2013). "Specifically, Wnt1 stimulates expansion of the myoepithelial compartment prior to tumor formation." (PMID 20107508, 2010). "Furthermore, by age 50 weeks, all of the bi-transgenic mice exhibited tumors, at which time about 25% of the Wnt1 transgenic mice (n = 31) still were tumor free." (PMID 20565980, 2010). "To determine what types of cells in the Wnt1 tumors express SDF1, we injected dissociated Wnt1 tumor cells into the mammary fat pads of immune-deficient Rag2−/−mice constitutively expressing an enhanced green fluorescent protein under control of the chicken β-actin promoter (EGFPtg/Rag2−/−)." (PMID 20087418, 2010). "Controversy concerning the role of PEA3 factors in carcinogenesis prompted us to further examine the role of this transcription factor family in mammary neoplasia, using the MMTV/Wnt1 mouse model in which tumor formation is driven by mammary-targeted expression of a Wnt1 transgene." (PMID 20107508, 2010). "A major distinction between Wnt1 and Her2 tumor epithelial cells is the presence of myoepithelial cells in Wnt1 tumors, which could account for the expression of SDF1." (PMID 20087418, 2010). "Although this tumor grew much faster than the previous Wnt1 tumor without H-ras mutation, a similar inhibition of tumor growth with anti-SDF1 antibody was seen (1,196 mm3 for anti-GD group vs. 716 mm3 for anti-SDF1 group; p<0.001)." (PMID 20087418, 2010).
tumor (continued). "The observation that Wnt1 induces specific amplification of the myoepithelial, or basal, compartment in Wnt1-expressing mammary gland prior to tumor formation suggests that these putative Wnt1-responsive progenitor cells may reside in the basal cell layer." (PMID 20107508, 2010). "Higher amounts of SDF1α proteins were also immunoprecipitated from Wnt1 tumor lysates than from Her2 tumor lysates, and higher amounts of secreted SDF1α proteins were detected in the media of cultured Wnt1 tumor cells vs. Her2 tumor cells." (PMID 20087418, 2010). "However, we observed changes in the Wnt-1 tumor histopathology, and a trend towards shorter survival in DMBA-treated SAFB1+/- mice." (PMID 19267898, 2009). "Genome-scale overview of the microarray data revealed that expression changes in the three tumor models of K19-C2mE, K19-Wnt1/C2mE and K19-Nog/C2mE were quite similar, whereas overexpression of Wnt1 only or Nog only led to the expression changes in a small portion of genes." (PMID 20015407, 2009). "Wnt1-ransformed progenitor cells might differentiate into multiple cells types, resulting in tumor heterogeneity." (PMID 19267898, 2009). "p-ERK1/2 levels were not stimulated by Wnt1 treatment of MDA-MB-231 tumor cells, which have a K-RAS mutation and high basal ERK1/2 activity." (PMID 17897439, 2007). "Evidence for this hypothesis is seen by the collagen structure associated with regions of invading cells in the Wnt-1 tumors, PyVT tumors, and MPLSM analysis of invasive regions in tumor histology sections." (PMID 17190588, 2006). "All Wnt1-induced tumors (n = 13) exhibited a type P tumor pattern." (PMID 15535849, 2004). "Gene array data also support a stem cell origin for neoplasms arising in mice transgenic for Wnt1." (PMID 15535849, 2004). "In addition, an anti-Wnt-1 monoclonal antibody has been shown to suppress tumour growth." (PMID 34572606, 2021). "Of note, Makoto and his colleagues showed that activated WNT signaling in the tumor stromal microenvironment contributes to the development of murine pancreatic MCNs in Ptf1a-Cre-LSL-Kras-elastase-tva mice injected with replication-competent-avian-sarcoma (RCAS)-WNT1 viruses." (PMID 33924999, 2021). "This lack of any effect on the early expansion of Wnt1-responsive cells upon FAK ablation or loss of its kinase activity could potentially account for at least in part the apparently similar tumor development for the three cohorts of mice Ctrl-Wnt1, cKD-Wnt1, and cKO-Wnt1." (PMID 32493400, 2020). "Modifications in DNA methylation pattern and also enrichment of methylated histone signs in the promoter regions of some certain genes like MUTYH, KLF4/6 and WNT1 in different signaling pathways could be a notable key contributors to the upregulation of tumor initiation in CRC." (PMID 31724937, 2019). "Additionally, LUAD was the tumor type with the lowest Wnt1-CD8a correlation z-score." (PMID 30926812, 2019). "Given that Wnt1-EarlyEx tumors share features with normal MaSCs and that Wnt1-LateEx tumors share features with normal LumProg cells, we hypothesized that these two Wnt1 classes might have different tumor-initiating potential." (PMID 31213486, 2019). "Moreover, the Wnt1/dnIGF-1R primary tumors displayed a tumor-promoting immune phenotype." (PMID 30458886, 2018). "Moreover a continuing effect of canonical Wnt signaling acting on tumor stem cells might account for the suppression of tumor growth in MMTV-Wnt1 transgenic mice when the Wnt1 signal is antagonized after progression to carcinoma." (PMID 25019931, 2014). "Furthermore, Sdc1 knockout mice and are resistant to Wnt1 induced tumor formation." (PMID 22936997, 2012).